TREML2 (triggering receptor expressed on myeloid cells like 2)
Description:
Cell surface receptor that may play a role in the innate and adaptive immune response. Acts as a counter-receptor for CD276 and interaction with CD276 on T-cells enhances T-cell activation.
Synonyms: TLT-2; C6orf76; TLT2; FLJ13693; dJ238O23.1
Tractability: Antibody: its Gene Ontology location is reachable by antibodies, with high confidence; UniProt places it where antibodies can reach, with medium confidence; UniProt predicts a signal peptide or a membrane-spanning region.
Gene: Protein-coding gene on chromosome 6 (41,189,749 to 41,201,149, reverse strand). Ensembl gene ENSG00000112195.
Subcellular location: Cell membrane
Pathways (Reactome):
Immune System: Immunoregulatory interactions between a Lymphoid and a non-Lymphoid cell
Gene Ontology:
Molecular function: protein binding; signaling receptor activity
Biological process: T cell activation
Cellular component: cell surface; plasma membrane
Genetic constraint (gnomAD): Loss-of-function variants: 26 observed, 26.44 expected, observed/expected ratio (o/e) 0.98, 90% interval 0.72 to 1.36. The upper end of that interval is the gene's LOEUF score, 1.36, which puts it in group 5 of 6, group 1 being the genes least tolerant of losing a copy. Missense variants: 359 observed, 403.21 expected, observed/expected ratio (o/e) 0.89, 90% interval 0.82 to 0.97. Synonymous variants: 139 observed, 154.76 expected, observed/expected ratio (o/e) 0.9, 90% interval 0.78 to 1.03.
Homologues: Orthologues: chimpanzee TREML2 (98% identical), macaque TREML2 (91% identical), dog TREML2 (67% identical), rabbit TREML2 (62% identical), mouse Treml2 (52% identical), rat Treml2 (50% identical), guinea pig Treml2 (43% identical), tropical clawed frog trem2 (15% identical). Paralogues in human: NCR2 (17% identical), TREML4 (15% identical).
Diseases named in the same sentence as TREML2 in open-access papers:
TREML2 is named in the same sentence as 25 diseases in open-access papers, as found by Europe PMC text mining. Sharing a sentence is not in itself a finding about the gene and the disease. The quoted sentences say what the papers report.
Alzheimer disease (6 papers, 2014 to 2025). A progressive, neurodegenerative disease characterized by loss of function and death of nerve cells in several areas of the brain leading to loss of cognitive function such as memory and language. "Particularly, TREML-1 can enhance the calcium signalling in an SHP2 (PTPN11)-dependent manner, whereas some genetic variant of TREML-2 have been identified to be protective for Alzheimer’s disease, contrary to TREM-2 genetic variants." (PMID 40948752, 2025). "In the present study, to uncover the possible mechanisms by which TREML2 rs3747742‐C reduces AD risk, we investigated the possible relation of this variant with AD‐related brain structures using a cognitively normal elderly population from Alzheimer's Disease Neuroimaging Initiative (ADNI) database." (PMID 32073739, 2020). "In Alzheimer’s disease, TREML2 knockdown suppresses neuroinflammation by inhibiting NLRP3 inflammasome activation and inducing M2 microglial polarization in primary microglia." (PMID 38745316, 2024). "A coding missense mutation (rs3747742) in triggering receptor expressed on myeloid cell-like 2 (TREML2) has been recently proposed as an important protective factor against Alzheimer’s disease (AD)." (PMID 31156362, 2019). "Although the common pathology of Alzheimer’s disease (AD) and white matter hyperintensities (WMH) is disputed, the gene TREML2 has been implicated in both conditions: its whole-blood gene expression was associated with WMH volume and its missense variant rs3747742 with AD risk." (PMID 36430248, 2022). "This study is the first one designed to analyze the role of TREML2 rs3747742 in the pathogenesis of AD by examining the relation of rs3747742 with CSF proteins, neuroimaging biomarkers and cognitive function in the Alzheimer’s Disease Neuroimaging Initiative (ADNI) database." (PMID 31156362, 2019). "Moreover, finding new molecules that can act via TREML-1 could modulate the activity of TREM-2, and vice-versa On the other hand, also targeting TREML-2 could open to new strategies for the treatment of Alzheimer’s disease, highly enhancing the rate of success." (PMID 40948752, 2025).
Cognitive impairment (2 papers, 2019 to 2023). Abnormal cognition is characterized by deficits in thinking, reasoning, or remembering. "With the exception of this individual, all other carriers had substitutions at loci rs3851179 (intergenic, chromosome 11), rs3747742 (TREML2 missense variant, chromosome 6), and rs1990621 (intergenic, chromosome 7), which previously have been shown to be protective against cognitive impairment." (PMID 37953886, 2023). "Finally, we observed that only in AD patients, but not in normal controls or mild cognitive impairment (MCI) individuals, TREML2 rs3747742 exhibited a strong association with CSF total-tau levels at baseline (β = -22.1210, p = 0.0166) and 4-year follow-up (β = -0.3961, p = 0.0115)." (PMID 31156362, 2019).
asthma (1 paper, 2024). "Testing for differential DNAm by asthma status, we found only five of these CpGs to be DMCs (i.e. significant for asthma at the Bonferroni level of p < 0.05/915): two CpGs for FKBP5 (cg03546163, cg23416081), two for TREML2 (cg26928682, cg18297196) and one for TMEM71 (cg27159719)." (PMID 38806494, 2024).
Brain atrophy (1 paper, 2022). Partial or complete wasting (loss) of brain tissue that was once present. "Using data from the extensively phenotyped population-based Study of Health in Pomerania we found associations of TREML2 with WMH volume and AD-related brain atrophy on different molecular levels." (PMID 36430248, 2022). "In sum, TREML2 robustly associated with WMH volume and AD-related brain atrophy on different molecular levels." (PMID 36430248, 2022). "In the current study, we found an association between TREML2 gene expression in whole-blood and WMH volume, but not our AD score measuring AD-related brain atrophy." (PMID 36430248, 2022).
leukaemia (1 paper, 2024). "After correcting for multiple testing (0.05/533 exGS tests), we identified 28 associations, including 24 for NHL, 2 for leukaemia (SRP14, TREML2), 1 for both liver (KRT18) and lung cancer (TNR)." (PMID 38750076, 2024).
osteoporosis (1 paper, 2014). A condition of reduced bone mass, with decreased cortical thickness and a decrease in the number and size of the trabeculae of cancellous bone (but normal chemical composition), resulting in increased fracture incidence. "Several other genes such as TREML2, HTR1E, and GLO1 are shown to be novel susceptible genes for osteoporosis, as confirmed from other studies." (PMID 25364766, 2014). "Three shared genes (“TREML2,” “HTR1E,” and “GLO1”) may have important biological functions related to BMD associated with osteoporosis." (PMID 25364766, 2014).
type 1 diabetes (1 paper, 2021). "This shape-based nature enabled us to discover multiple unique protein–phenotype links, including cathepsin H and type 1 diabetes (rs2289702 within CTSH), TREM-like transcript 2 protein and monocyte count (rs62396355 within TREML2) or plexin-B2 and systolic blood pressure (rs28379706 within PLXNB2)." (PMID 34819519, 2021).
cancer (2 papers, 2024 to 2025). A tumor composed of atypical neoplastic, often pleomorphic cells that invade other tissues. "Representative images of immunohistochemical stains of TREMs family genes (lacking TREML2) in ovarian normal and cancer tissues were acquired from the Human Protein Atlas online database." (PMID 39744496, 2025).
hematological malignancies (1 paper, 2024). "When using ML for predicting the important prognostic genes for AML, TREML2 was one of the top 6 with high AUC of 0.9, further confirming its importance in hematological malignancies." (PMID 38650628, 2024).
TREML2 also shares sentences with these, for which no sentence is quoted: tumor (5 papers); infection (2); tuberculosis (2); atherosclerosis (1); bacterial infection (1); cerebral small vessel disease (1); E. coli infection (1); lung carcinoma (1); melanoma (1); neurodegenerative disease (1); placental insufficiency (1); psoriasis (1); pulmonary tuberculosis (1); Sepsis (1); type 2 diabetes (1); white matter hyperintensities (1).